ANXA2 (annexin A2)
Diseases named in the same sentence as ANXA2 in open-access papers (continued):
Sharing a sentence is not in itself a finding about the gene and the disease.
tumor (continued). "All together, these data show that the expression of INHBB, ANXA2, and TGFA ligands could be specifically up-modulated in PTCs vs. normal contralateral cells, thus supporting the hypothesis that their differential expression is finely regulated in normal tissues vs. tumor tissues." (PMID 20877637, 2010). "By integrating functional tumor assays and mechanistic analysis, our study is the first to report that VSIG2 acts as a membrane-anchored negative regulator of ANXA2 trafficking rather than a classical immune checkpoint." (PMID 41185558, 2025). "ANXA2 expression was upregulated in RCC samples, compared with non-tumor kidney tissues (P < 0.001)." (PMID 38519766, 2024). "A recent study has shown that the actin cytoskeleton regulated by ANXA2 has a negative effect on T cell aggregation, which may be one of the mechanisms by which upregulation of ANXA2 expression in tumors leads to reduced T cell activation and immune imbalance in the tumor microenvironment." (PMID 34675316, 2021). "Cell-surface AnxA2 in complex with S100A10, finally, is a key factor in both malignant and non-malignant angiogenesis, and it contributes to tumor cell invasion and metastasis within an inflammatory microenvironment." (PMID 32575495, 2020). "GB is a highly invasive tumor, interestingly we found that hypoxia did not induce MMP-2, MMP-9, PLAU, uPAR, CTSA, or ANXA2 gene transcription in our GB cell models." (PMID 32867190, 2020). "Compared with the non-tumorous corresponding tissues, the phosphorylation of AnxA2 at Tyr23 and total AnxA2 were observed in 90.0% (9/10) and 80.0% (8/10) of TNBC tumor tissue samples, respectively." (PMID 33374917, 2020). "Intriguingly, ANXA2 was also expressed in the proximal convoluted tubules, which is thought to be the origin of RCC, of younger fetal kidneys, and reappeared in clear cell RCC tumor cells, but not in that of normal adult kidneys." (PMID 36120574, 2022). "In addition, when we evaluated liver tissues of five patients with HCC, the protein expression of AKR1B10, ZNF468, annexin A2 (ANXA2), and CD24 was increased in tumor tissue compared with surrounding nontumor tissues." (PMID 35563425, 2022). "Tumor bearing mice treated with Lm-ANXA2 without CD8+ T cell depletion had significantly superior survival than those mice treated with Lm-ANXA2 and concurrent CD8+ T cell depletion throughout the treatment period, suggesting that the anti-tumor effect of Lm-ANXA2 is mediated by CD8+ T cells." (PMID 31113479, 2019).
cancer (347 papers, 2005 to 2025). A tumor composed of atypical neoplastic, often pleomorphic cells that invade other tissues. "Previous studies have shown that ANXA2 is associated with poor prognosis and metastasis in breast and various other cancers and that ANXA2 enhances osteoclast formation and bone resorption." (PMID 40837013, 2025). "It has been established that abnormal regulation of ANXA2, which is a protein that binds phospholipids and is dependent on calcium, is linked to a number of different types of cancer." (PMID 38711550, 2024). "Previous studies have shown that ANXA2 is upregulated in many types of cancers and its higher expression levels are associated with poorer overall survival (OS) and shorter disease-free survival (DFS)." (PMID 38658569, 2024). "The ANXA2 expression was associated with the clinical T stage of five types of cancer, the clinical N stage of five types of cancer and the clinical M stage of four types of cancer, supporting a potential prognostic value in these tumors." (PMID 36713082, 2023). "The high expression of Annexin A2 was significantly associated with a reduced overall survival, disease-specific survival and progression-free interval in seven cancers." (PMID 36713082, 2023). "Owing to the deficiency of relevant pan-cancer research and the important function of ANXA2 in tumors, a comprehensive pan-cancer analysis of ANXA2 were conducted using various databases." (PMID 36713082, 2023). "We further explored the association between the ANXA2 gene expression and infiltration of 24 types of immune cells in pan-cancer." (PMID 36713082, 2023). "The pan-cancer survival analysis of ANXA2 gene based on the GEPIA database showed that high expression of ANXA2 was associated with lower overall survival in all 33 types of cancer (p = 0)." (PMID 36713082, 2023). "ANXA2 gene expression was associated with varying levels of immune infiltration in 32 types of cancer (except CHOL) according to the findings." (PMID 36713082, 2023). "The diagnostic and prognostic abilities of ANXA2 in various cancers suggest its potential as a marker for the early diagnosis." (PMID 36713082, 2023). "The Spearman’s correlation coefficient was used to indicate the association between the gene expression of ANXA2 and immune infiltration in 33 types of cancer." (PMID 36713082, 2023). "A survival analysis was conducted to examine the association between ANXA2 expression and prognosis of 33 types of cancer." (PMID 36713082, 2023). "The application of bioinformatics technology can provide us with the valuable theoretical basis of the pathogenic role of ANXA2 in pan-cancer." (PMID 36713082, 2023). "We demonstrate that the deficiency in ANXA2 inhibits response of cancer cells to shear stress, which leads to cell death due to the absence of membrane repair." (PMID 38092984, 2023). "ANXA2 has been linked to cancers including ovarian, colorectal, breast and lung cancer; it has also been identified as a key mediator of HPV entry and intracellular trafficking." (PMID 37185759, 2023). "Of these, HSPA8, HSPA9, PKM, HNRNPA1, NPM1, ANXA2 are already reported to be associated with LN metastasis in GBC or other cancers." (PMID 37142981, 2023). "This oncogenic function of S100A10 was associated with its capability to form complexes with ANXA2, another potent oncogene in many cancers." (PMID 36232334, 2022). "The Anxa2 gene encodes calcium-dependent phospholipid-binding protein ANXA2, and is a key contributor to several hallmarks of cancer, including cancer cell proliferation, inhibition of apoptosis, cell adhesion, invasion, metastasis, and angiogenesis." (PMID 36612019, 2022). "Annexin A2 is known to be highly expressed in the cancer cells, and its expression level is directly linked to their proliferation and invasion ability." (PMID 35163891, 2022). "Detection of ANXA2 level is of interest due to its prognostic and diagnostic significance in cancer treatment." (PMID 33995636, 2021).
cancer (continued). "Aberrant expression of ANXA2 can be used as a potential predictive factor, diagnostic biomarker and therapeutic target in cancer therapy." (PMID 33995636, 2021). "Annexin A2 (AnxA2), a 36-kDa calcium-dependent phospholipid-binding protein, was associated with various cancer-associated plasminogen activation, actin-cytoskeletal rearrangement, cellular adhesion, and migration." (PMID 34039961, 2021). "The cancer pathway is also associated with two genes implicated in the cytoskeletal remodeling and network, ANXA2 and TUBA1A, linked to HCC and cell migration (i.e., metastasis development) thus predicting the fate of the NASH." (PMID 31717414, 2019). "Annexin A2, a multi-functional cancer associated protein, promotes cancer progress in a list of mechanisms." (PMID 29508276, 2018). "This highlights the potential role of AnxA2 in cancer associated fibroblasts and the potential value for stromal AnxA2 to serve as a biomarker in patients with PDA." (PMID 29290958, 2017). "ANXA2 overexpression was positively correlated with advanced cancer phenotypes, whereas ANXA4 expression was associated with resistance to radiation with or without chemotherapy (p = 0.029)." (PMID 27402115, 2016). "Anxa2 is a hotspot molecule with potential to be a diagnostic and prognostic marker for certain cancers." (PMID 26307676, 2015). "Annexin A2, a regulator of plasmin formation and signalling, is implicated in cancer with its levels elevated in various tumors." (PMID 25878399, 2015). "Several reports have shown that upregulation of annexin A2 levels is positively associated with cancer progression and chemoresistance." (PMID 23434659, 2013). "We reasoned that if ANXA2 plays a role in cellular redox regulation its depletion will render cancer cells more susceptible to ROS induced damage/death during tumorigenesis." (PMID 22185818, 2011). "MIEN1 and Annexin A2 have been implicated in cancer progression and metastasis, but their modulation can also dampen inflammatory responses, suggesting potential for integrated sepsis and cancer therapies." (PMID 40563999, 2025). "This study examined the diagnostic and prognostic efficacy of ANXA2 in 33 types of cancer." (PMID 36713082, 2023). "The ROC curve was used to evaluate the diagnostic efficacy of ANXA2 in 33 types of cancer." (PMID 36713082, 2023). "ANXA2 was variably associated with immunomodulators studied in all the tumors (p < .05) and positively associated with most immunomodulators in 30 types of cancer (except CESC, HNSC and LUSC)." (PMID 36713082, 2023). "Annexin A2 showed a good diagnostic efficacy in twelve types of cancer." (PMID 36713082, 2023). "In addition to our findings, several other studies have linked Annexin A2 to cancer progression as reviewed in." (PMID 37941562, 2023). "Annexin A2 has been extensively implicated in tumorigenesis and development in previous studies, but its precise role in pan-cancer remains largely unknown." (PMID 36713082, 2023). "Upregulation of AnxA2 is generally associated with an aggressive and metastatic cancer phenotype, as well as resistance to chemotherapy, being directly related with advanced clinical stages of several cancer types such as lung, breast and colorectal tumors as well as neuronal malignancies." (PMID 37250892, 2023). "Aberrant expression of ANXA2 was associated with the development of many cancers." (PMID 36324154, 2022). "In addition, this increase in ANXA2 expression is linked to a worse clinical outcome and cancer recurrence in patients with metastatic PCa6." (PMID 36224238, 2022). "Interestingly, within the pulmonary vasculature, AnxA2 has now been found responsible for the severe side effects caused by bleomycin, a clinically potent anticancer drug for a large variety of cancers." (PMID 33810523, 2021).
cancer (continued). "This secretory function of AnxA2 may extend to other disorders associated with COL6 deficiency or exocytic events driving cancer progression." (PMID 33810523, 2021). "On the other hand, ANXA2 performs the function of a diagnostic factor for screening cancers." (PMID 33995636, 2021). "In addition, Annexin A2 has a known clinical association with cancer and has a role downstream of growth factor signaling pathways such as the IGF-IR and the EGFR pathways." (PMID 32629869, 2020). "Furthermore, a number of studies have linked growth factor mediated phosphorylation of Annexin A2 to the promotion of EMT in a variety cancer types." (PMID 32629869, 2020). "We proposed that Anxa2 functions downstream of Rack1 to promote the aggressive behavior in drug-resistant cells given that Rack1 binds and regulates Anxa2 phosphorylation, and Anxa2 is a key protein causing drug resistance and enhancement of cancer metastasis." (PMID 31113450, 2019). "Annexin A2 (ANXA2) has been well known to associate with the progress of malignant tumor." (PMID 31186633, 2019). "On the other hand, ANXA2 serves as a diagnostic factor for screening cancers." (PMID 29598816, 2018). "Moreover, MTCO2 and Anxa2 were reported to be associated with radio-resistance and as biomarkers of cancer stem cells, respectively." (PMID 29298329, 2018). "ANXA2 has multiple potential N-linked and O-linked glycosylation sites and glycoforms of ANXA2 have been reported in multiple cell types including cancer." (PMID 29568351, 2018). "Importantly, extracellular ANXA2 is associated with many human diseases, such as cancers, inflammatory disorders and autoimmune diseases." (PMID 28720835, 2017). "ANXA2 expression was associated with a more aggressive cancer phenotype." (PMID 27402115, 2016). "We also confirmed these findings by GSEA of ANXA2-inhibited GBM cells, which shows a significant negative enrichment of gene signatures associated to undifferentiated cancer and stem cell phenotype, suggesting the potential involvement of ANXA2 also as a modulator of differentiation in GBM cells." (PMID 27429043, 2016). "In this context, Annexin 2A (ANXA2) is a phospholipid-binding protein expressed in a variety of cell types, whose expression has been recently associated with cell dissemination and metastasis in many cancer types, thus making ANXA2 an attractive putative regulator of cell invasion also in GBM." (PMID 27429043, 2016). "ANXA2 is upregulated in several cancers and is associated with metastasis." (PMID 26196246, 2015). "In the future, ANXA2 may be a potential prognostic factor, a potential diagnostic factor for cancer, and a therapeutic target for new drug development after analysis in large scale, well-controlled, prospective clinical trials." (PMID 24591759, 2014). "It was suggested that exosomal annexin A2 could serve as a diagnostic tool and as a biomarker in cancer progression and prognosis." (PMID 23519104, 2013). "The cell surface associated AnxA2 heterotetramer, is a receptor for both plasminogen and tissue type plasminogen activator (tPA) and acts as a catalytic center for the activation of plasminogen to plasmin which helps in invasion and metastasis of cancer cells." (PMID 22957061, 2012). "Although controversial, ANXA2 has also been implicated in other cellular processes, in particular plasmin activation, which could also contribute to cancer progression." (PMID 22185818, 2011). "Several reports have shown that up-regulation of ANXA2 levels is positively associated with cancer progression and chemoresistance, nevertheless the function of ANXA2 during these processes remained unknown." (PMID 22185818, 2011). "The linear detection of ANXA2 by HsGDY ranged from 0.01 fg/mL to 1000 ng/mL, and the electrochemical results obtained demonstrated a high degree of correlation with the concentrations of ANXA2 cancer biomarkers in patients obtained by enzyme-linked immunosorbent assay." (PMID 40038692, 2025).
cancer (continued). "In addition to that, ANXA2 is continuously being tested as a potential diagnostic and prognostic biomarker for many cancers, something that could significantly help in patients’ management." (PMID 39594718, 2024). "Thus, abnormal Anxa2 expression may serve as a cancer diagnostic biomarker, predictive factor, and therapeutic target." (PMID 37955107, 2023). "Post-translationally modified MIEN1 interacts with Syk kinase and Annexin A2 protein; polymerizes G-actin and stabilizes F-actin filament; induces focal adhesion kinase phosphorylation and decrease cofilin phosphorylation implicated in both invasion and metastasis of different cancer types." (PMID 31552186, 2019). "Localisation of AnxA2 to the extracellular surface of the plasma membrane, facilitated by lipid raft endocytosis and exosomal transport, has been found in many cell types, including endothelial cells (ECs), macrophages as well as cancer cells associated with lymphoma or leukemia." (PMID 23555942, 2013). "Annexin A2 in its heterotetrameric form, AIIt, has also been implicated in other cellular processes, in particular, plasmin activation, which could also contribute to cancer progression." (PMID 23434659, 2013). "Subsequent analysis of CD86 and CD163 mRNA expression in TAMs cocultured with cancer cells revealed that ANXA2 knockdown increased CD86 expression but suppressed CD163 expression compared with those in the control group." (PMID 39972459, 2025). "Building on these mechanistic insights, we further discuss the clinical potential of ANXA2 in prognosis and cancer therapy." (PMID 40234383, 2025). "Currently, most research focuses on ANXA2’s involvement in cell division processes, primarily within the context of cancer." (PMID 40141747, 2025). "Through correlation analysis, we observed that LAD1 expression levels were statistically associated with several cancer-related genes, including SFTPB, S100A6, CEACAM6, KRT19, S100A10, ANXA2, S100A11, and CAPN2." (PMID 41423496, 2025). "The ACE4 aptamer, selected via Cell-SELEX, binds ANXA2 and inhibits its function across cancer models, particularly in MCF-7 cells." (PMID 40234383, 2025). "Currently, there are numerous studies indicating the involvement of ANXA2 in the development of cancer." (PMID 40141747, 2025). "Annexin A2 (ANXA2) is a multifunctional protein that binds to calcium and phospholipids and plays a critical role in various pathological conditions, including cancer and inflammation." (PMID 40234383, 2025). "Conversely, in various cancer cell lines (MCF-7, A549, HT1080, LLC, and 293T) with ANXA2 deficiency, elevated ROS levels, enhanced activation of pro-apoptotic kinases, and increased sensitivity to ROS were also observed." (PMID 40141747, 2025). "The data on the involvement of ANXA2 in cancer development are summarized in numerous reviews, including those focusing on glioblastoma and the function of the AIIt complex as a receptor for tPA and plasminogen." (PMID 40141747, 2025). "ANXA2 which showed higher expression in UC compared with CD in this study, is an important member of the annexin family with a role in cancer progression and inflammation." (PMID 41036804, 2025). "Several studies highlighted the noticeable function of Anxa2 phosphorylation at Tyr23 in regulating cancer metastasis through its interaction with EGFR." (PMID 39912333, 2025). "This review looks at the current understanding of how Annexin A2 is involved in cancers of the digestive system, including its potential to help diagnose cancer, predict how a patient will respond to treatment, and even serve as a target for new therapies." (PMID 39594718, 2024). "In postoperative patients, after gemcitabine adjuvant chemotherapy, ANXA2 overexpression, as well as a high degree of ANXA2 staining in the cancer cells, correlated with a rapid recurrence." (PMID 39594718, 2024). "ANXA2, a 36 kDa protein, is involved in autoimmune and neurodegenerative diseases and malignant tumours." (PMID 37782406, 2024).